INS (insulin)
Diseases named in the same sentence as INS in open-access papers (continued):
Sharing a sentence is not in itself a finding about the gene and the disease.
Insulin resistance (continued). "High collinearity between insulin-related indices (VIF > 8) indicates overlapping effects among markers of insulin resistance and lipid metabolism, potentially obscuring independent associations." (PMID 41596434, 2026). "In obese mammals, preventing chronic hyperinsulinemia or lowering basal insulin levels improves insulin resistance, hepatic steatosis, and inflammation while extending lifespan." (PMID 41189469, 2026). "One model for the development of T2D is that in a calorie-rich environment, over-production of insulin leads to increased uptake of glucose and storage of energy, leading to obesity and insulin resistance." (PMID 41386533, 2026). "Insulin resistance and hyperinsulinemia further exacerbate OA progression, with elevated insulin levels inducing abnormal chondrocyte differentiation and cartilage hypertrophy, thus accelerating cartilage degeneration." (PMID 40761349, 2025). "Insulin resistance increases markedly in pregnant individuals after 24 weeks, and when pancreatic insulin secretion is insufficient to maintain euglycemia, hyperglycemia develops." (PMID 40807035, 2025). "These composite indices appear useful for insulin resistance assessment when insulin measurement is unavailable or unreliable." (PMID 41465784, 2025). "The two main proposed mechanisms involve an indirect effect through modulation of insulin resistance—by reducing insulin IGF1 (Insulin like Growth Factor) signaling and controlling hyperglycemia—as well as a direct effect on cell cycling and apoptosis." (PMID 41156128, 2025). "ROS can directly or indirectly interact with the insulin signaling pathway and induce insulin resistance." (PMID 39873298, 2025). "In patients with Type 2 diabetes, CRP levels also showed a significant upward trend and were independently correlated with insulin resistance, insulin secretion, and lipid profiles." (PMID 41293068, 2025). "Insulin resistance during pregnancy can be overcome by the release of more insulin into the blood by pancreas β-cells." (PMID 41536823, 2025). "Under insulin resistance, Akt, the downstream of insulin signaling is inhibited, leading to the upregulation of GSK3β, which causes β-catenin degradation and ultimately compromises bone formation effect of Wnt signaling." (PMID 40149867, 2025). "Insulin resistance is a state in which peripheral tissues, particularly muscle, fat, and liver, fail to respond adequately to insulin, resulting in impaired GLUT4-mediated glucose transport due to defective translocation of GLUT4 to the cell surface." (PMID 40862756, 2025). "Such biomarkers as fasting insulin, the homeostasis model assessment of insulin resistance (HOMA-IR) index, C-reactive protein, and markers of mitochondrial biogenesis PGC-1α and Tfam improve our understanding of metabolic balance." (PMID 39940866, 2025). "It enhances PDX1 expression and nuclear localization, which supports β-cell identity, promotes proliferation, and boosts insulin production—processes essential for maintaining β-cell function and compensating for insulin resistance." (PMID 41300804, 2025). "Studies have shown that free fatty acids released from visceral fat interfere with insulin signaling, leading to insulin resistance." (PMID 40013161, 2025). "The fundamental process involves insulin resistance and β-cell dysfunction, wherein insulin impairs insulin production, leading to fast oscillations and diminished amplitude of substantial insulin pulses." (PMID 40004770, 2025). "At the cellular level, elevation of TNF-α levels produced by adipocytes and/or peripheral tissues induces insulin resistance by impairing the insulin signaling pathway through serine phosphorylation." (PMID 40048497, 2025). "Glucose tolerance and insulin resistance were evaluated through glucose tolerance tests (GTTs) and insulin tolerance tests (ITTs)." (PMID 40647186, 2025).
Insulin resistance (continued). "Insulin resistance (IR) is defined as the inability to achieve a normal physiological plasma glucose disposal rate at the normal physiological plasma insulin level; hence, it results in an increased fasting plasma insulin level." (PMID 41424588, 2025). "ER resistance repressed the insulin-assisted uptake of glucose, and hyperinsulinemia was observed as a counteraction to deepening insulin resistance." (PMID 41514592, 2025). "In T2D, β-cells fail to secrete sufficient insulin, leading to insulin resistance in peripheral tissues." (PMID 39968090, 2025). "This disruption impairs insulin signaling, contributing to the development of insulin resistance in T2D." (PMID 40127075, 2025). "As expected, body weight, FFM, fasting plasma insulin, C-peptide, and the Homeostatic Model Assessment for Insulin Resistance (HOMA-IR2) were lower after than before surgery." (PMID 40474966, 2025). "Given that AGEs also impair insulin signaling through receptor-mediated oxidative stress and inflammatory pathways, their accumulation may represent a common mechanistic link between reduced sudomotor function and insulin resistance in T1D, thereby amplifying the risk of neuropathic progression." (PMID 41257477, 2025). "Surrogate insulin resistance indices serve as more straightforward and practical alternatives to insulin-based markers of insulin resistance for clinical application." (PMID 41422312, 2025). "Insulin resistance and impaired insulin secretion are the primary mechanisms in the development of T2DM." (PMID 40612313, 2025). "Inflammation also causes insulin resistance, and it is shown that TNF-α stimulates phosphorylation of IRS-1ser307, leading to suppression of insulin/IGF-1 signaling." (PMID 38811433, 2025). "A cohort study from China found similar seasonal insulin changes, linking elevated PM2.5 to increased insulin resistance, particularly among those with underlying metabolic disorders." (PMID 40863890, 2025). "Baduanjin consistently improved glycemic parameters, including FBG, 2hPG, insulin resistance, and HbA1c, likely due to its moderate intensity, rhythmic movements that enhance skeletal muscle glucose uptake and improve insulin sensitivity." (PMID 41255514, 2025). "Among different cytokines, we selected TNF-α to confirm the effect of the proinflammatory cytokines on the differentiation of preadipocytes derived from individuals with insulin sensitivity and insulin resistance." (PMID 41574186, 2025). "Insulin resistance (IR) refers to a pathological state in which peripheral tissues and target organs exhibit diminished sensitivity to insulin, leading to impaired glucose uptake and utilization, and consequently contributing to hyperglycemia." (PMID 41471379, 2025). "A previous study on metformin—the parent compound of imeglimin—showed that it inhibits vesicular ATP release and purinergic signaling, thereby enhancing insulin signaling and improving insulin resistance in hepatocytes." (PMID 40948113, 2025). "In insulin resistance, impaired cellular sensitivity to insulin forces the pancreas to produce ever more insulin (hyperinsulinaemia) to regulate the flow of glucose from the blood into the cells and maintain homeostasis." (PMID 40901288, 2025). "More investigations are needed about the regulatory factors that control BLVRA and BLVRB expression and the bilR bacterial enzyme and their functional roles in fatty liver, MASLD, insulin resistance, insulin clearance, and T2DM." (PMID 39873298, 2025). "For over a decade, it has been apparent that lower exercise capacity is an early marker of impaired insulin sensitivity in the development of insulin resistance and T2D." (PMID 39996052, 2025). "Their involvement in impairing insulin signaling and counteracting insulin’s anti-inflammatory effects positions them as potential mediators of insulin resistance." (PMID 40722699, 2025).
Insulin resistance (continued). "Refined starches, prevalent in processed foods, can lead to rapid spikes in blood glucose and insulin levels, contributing to insulin resistance, obesity, and metabolic syndrome." (PMID 39940607, 2025). "Specifically, measurements such as the homeostatic model assessment for insulin resistance, haemoglobin A1C, and fasting blood glucose levels showed notable decreases, while insulin levels experienced a marked increase." (PMID 40958722, 2025). "The HOMA-IR index, calculated from fasting glucose and insulin levels, is a widely used surrogate marker for insulin resistance and plays a critical role in evaluating metabolic dysfunction associated with obesity." (PMID 41009518, 2025). "Adipose tissue is a key organ that responds to insulin actions and, by itself, can contribute to insulin resistance." (PMID 41002956, 2025). "TNF-α plays a central role in the pathogenesis of obesity by disrupting insulin signaling, promoting insulin resistance and metabolic dysfunction." (PMID 41011232, 2025). "South Asian and Nordic women with pGDM exhibited differences in insulin resistance profiles, with South Asians showing greater adipose tissue insulin resistance and inflammation." (PMID 40987939, 2025). "In patients with enhanced ketogenesis, insulin sensitivity was significantly better when assessed using Homeostatic Model Assessment for Insulin Resistance (HOMA-IR, 3.4 ± 2.9 vs. 6.0 ± 5.2, p = 0.031)." (PMID 40943485, 2025). "IRS-knockout (KO) animals exhibit growth retardation and diabetic symptoms, including insulin resistance and obesity, suggesting that IRSs are essential for the biological activities of insulin/IGF-I." (PMID 39859555, 2025). "In the pancreas, GSK3 negatively affects insulin release and β-cell function, resulting in β-cell dysfunction and the development of insulin resistance." (PMID 40218884, 2025). "Pancreatic hormones, including insulin and glucagon, show improved β-cell function and insulin sensitivity, reflected in decreased homeostasis model assessment insulin resistance (HOMA-IR)." (PMID 41155711, 2025). "Some studies have shown that a diet rich in antioxidants, which reduce ROS levels, can improve glucose metabolism regulation, promote insulin secretion, and decrease insulin resistance." (PMID 40732969, 2025). "Specifically, serum sVCAM-1 levels demonstrated a positive relationship with serum insulin levels, C-peptide, and insulin resistance indices HOMA2-IR and HOMA2-B% after multivariable adjustment." (PMID 40094867, 2025). "The “gold standard” for assessing peripheral insulin resistance is time-consuming and labor-intensive, requiring insulin level measurements, which limits its feasibility in clinical practice, especially in primary care." (PMID 39974368, 2025). "When used in combination with liraglutide, a GLP-1 analog with known insulin-sensitizing effects, insulin-induced pGSK3β levels were restored to control values, indicating reversibility of inflammation-induced insulin resistance." (PMID 40724831, 2025). "Results showed that semaglutide significantly reduced the body weight, body fat, FBG, and insulin levels induced by high-fat diet, and improved insulin resistance and sensitivity damage (p < 0.05)." (PMID 40552153, 2025). "Conversely, in insulin resistance, including obesity and aging, increased insulin and IGF-1 signaling together promote inflammation." (PMID 41514592, 2025). "Type 2 diabetes is marked by both insulin resistance and impaired beta-cell function, leading to insufficient insulin production." (PMID 41280964, 2025). "Enhanced insulin sensitivity following quercetin administration was observed in several experimental models of insulin resistance: STZ/NA rats, db/db mice, and in mice fed an HFD." (PMID 40806520, 2025).
Insulin resistance (continued). "It has been unveiled that glucose dyshomeostasis, insulin resistance and impaired insulin signaling are promotive to the pathology of Alzheimer's disease as reflected by enhanced accumulation of Aβ and hyperphosphorylated tau." (PMID 40989573, 2025). "Insulin resistance (IR) is a hallmark of T2DM and occurs when there is a suboptimal response to physiological or elevated levels of insulin in insulin-sensitive organs." (PMID 41011980, 2025). "The TyG index, an insulin-independent ratio, has emerged as a valuable marker for identifying insulin resistance and has been increasingly investigated as a predictive tool for GDM." (PMID 41225974, 2025). "With insulin resistance, defectiveness or dysregulation of an insulin signaling component leads to impaired glucose metabolism." (PMID 40013621, 2025). "Many of the previous studies used a simplistic HOMA equation based on fasting insulin and glucose which models hepatic insulin resistance." (PMID 41146360, 2025). "Diabetes mellitus is a multifaceted metabolic disorder defined by chronic hyperglycemia, resulting from insufficient insulin production, insulin resistance, or both, and accompanied by disturbances in lipid, protein, and mineral metabolism." (PMID 40565043, 2025). "These intermediates, such as acylcarnitines, can directly contribute to insulin resistance, as they impair insulin signaling and induce metabolic inflexibility." (PMID 41226411, 2025). "Aerobic exercise contributes to reductions in body fat and enhances the sensitivity and responsiveness of peripheral target tissues to insulin through skeletal muscle activation, thereby promoting glucose utilization and mitigating insulin resistance." (PMID 41255539, 2025). "Inflammation-driven processes in the innate immune system can lead to apoptosis, tissue fibrosis, and organ dysfunction, contributing to insulin resistance, impaired insulin secretion, and renal failure." (PMID 39827095, 2025). "Maternal FRU intake has also been linked to increased fasting insulin and impaired insulin sensitivity, while 20% HFCS supplementation induced insulin resistance via downregulation of hepatic gene expression in Sprague-Dawley rats." (PMID 40956393, 2025). "Due to the chronic low-grade inflammation that characterizes this syndrome, elevated TNF-α levels are associated with hyperandrogenism, the development of insulin resistance and obesity because TNF-α interferes with insulin signaling." (PMID 40647668, 2025). "These conditions, in turn, contribute to adipocyte dysfunction, including impaired insulin signaling and the onset of metabolic disturbances such as insulin resistance." (PMID 41226331, 2025). "The CEACAM1-dependent endocytosis of insulin-bound insulin receptors facilitates the degradation of insulin and maintains the normal insulin half-life in the circulation, thereby preventing hyperinsulinemia and systemic insulin resistance." (PMID 40985048, 2025). "In pancreatic β-cells, FOXO1 controls insulin release and β-cell survival, and FOXO1 upregulation is associated with β-cell dysfunction in obesity and the pathogenesis of insulin resistance and T2D." (PMID 40218884, 2025). "On the other hand activation of the mTOR pathway can reduce insulin sensitivity and contribute to insulin resistance." (PMID 40036545, 2025). "The ‘insulin resistance’ pathway was only enriched at the initial time point in both families, as the ‘insulin signaling pathway’ was also up-regulated in the resistant family at 2 dpi." (PMID 41009783, 2025). "MPO has been shown to impair insulin signaling in hepatocytes, contributing to the development of insulin resistance." (PMID 39845896, 2025). "This is because overweight or obesity increases insulin resistance resulting in higher fetal glucose and insulin levels." (PMID 40460188, 2025).
Insulin resistance (continued). "On the other hand, insulin resistance would result in even larger needs for insulin and, thus, a vicious cycle of weight gain and increased total insulin dose would be established." (PMID 40760325, 2025). "PDAC-DM reflects two interacting processes: (i) insulin dysregulation driven by systemic insulin resistance and altered islet hormone signalling and (ii) insulin deficiency arising from β-cell stress, loss of identity, or cell loss." (PMID 41226286, 2025). "Chronic hyperglycemia and insulin resistance trigger compensatory hypersecretion of insulin, resulting in elevated blood insulin concentrations." (PMID 40806520, 2025). "Because iron overload is associated with the development of T2DM, it is possible to lead to reduced insulin secretion and insulin resistance through mechanisms such as widespread oxidative stress and altered insulin signaling pathways." (PMID 40474981, 2025). "Calculation of the Homeostasis model assessment of basal insulin resistance (HOMA-IR) values suggested that AT-specific SIRT3 overexpression improved insulin sensitivity in HFD-feeding." (PMID 40368890, 2025). "In type 2 diabetes (T2D), miR-146a acts as a molecular switch of insulin signaling and inflammation, and its dysregulation promotes insulin resistance and complications such as nephropathy, neuropathy, cardiovascular disease, and retinopathy." (PMID 41150807, 2025). "Insulin resistance, the central pathological feature in type 2 diabetes, is characterized by the reduced responsiveness of insulin-target tissue to insulin stimulation." (PMID 39859525, 2025). "Clinically, this would support the need for more widespread identification of insulin resistance in the type 1 diabetes population and an individualised approach to both insulin-sensitising adjunctive and antithrombotic therapies." (PMID 40304758, 2025). "Type 2 diabetes is characterized by chronic hyperglycaemia due to peripheral insulin resistance and malfunction of insulin secretion which results in glucose homeostasis dysregulation." (PMID 41190158, 2025). "These cytokines impair insulin signaling pathways and contribute to the onset of insulin resistance." (PMID 40231030, 2025). "Immune-metabolic markers included body mass index (BMI), fasting glucose (FG), fasting insulin, Homeostasis Model Assessment-Insulin Resistance (HOMA2-IR), C reactive protein and blood lipids." (PMID 41005771, 2025). "The dogma views hyperinsulinemia as a compensatory response to insulin resistance in insulin-sensitive tissues such as muscle, liver, and adipose tissue." (PMID 40868096, 2025). "HI treatment given to HepG2 cells in different conditions in various studies indicate that elevated insulin levels can foster insulin resistance." (PMID 40311678, 2025). "In turn, has been shown that this sustained inflammation impairs insulin signalling, contributing to systemic insulin resistance and the progression of metabolic disorders." (PMID 41226484, 2025). "Insulin resistance (IR) is a metabolic disorder characterized by reduced insulin action in target tissues, leading to impaired glucose homeostasis and type 2 diabetes mellitus (T2DM)." (PMID 40278260, 2025). "Overall, the presented results show the significant role of mitochondria in visceral adipose tissue in relation to insulin resistance, lipid metabolism, and the insulin signaling pathway." (PMID 40806527, 2025). "Further investigations are warranted to explore the interactions between METS-IR and other metabolic biomarkers (e.g., fasting insulin, FFAs, leptin, adiponectin) to clarify the mechanistic pathways of insulin resistance in NAFLD pathogenesis." (PMID 40640543, 2025). "Insulin resistance in skeletal muscle is likely a critical factor in developing MS, as skeletal muscle is responsible for 70–90% of insulin-stimulated glucose uptake." (PMID 40282872, 2025).